CD4 (CD4 molecule)
Diseases named in the same sentence as CD4 in open-access papers (continued):
Sharing a sentence is not in itself a finding about the gene and the disease.
tumor (continued). "The decrease in CD4, CD25 T cells complemented a higher ratio of the percentage of CD8:CD4, CD25 T cells (p = 0.0074), which correlates with increased anti-tumor activity by CD8 T cells." (PMID 34638488, 2021). "Tumour infiltrating lymphocytes (TILs), including T cells, B cells and NK cells, that exhibited anti‐tumoural functions, especially CD8 + and CD4 + T cells were infiltrated in low‐level RAD51AP1 group." (PMID 33314567, 2021). "IL-4 can promote development of specific immune cell subtypes, such as macrophages, B cells, CD4+Th2 cells, and CD8+ T cells, which play a pivotal role in the tumor progression of inflammation-related cancers, including HCC." (PMID 33906302, 2021). "Ki67 identified proliferating CD8+ T cells (median 4.3/mm2, 14.7% of CD8+ cells), CD4+ T cells (median 1.3/mm2, 31.1% of CD4+ cells), and B cells (median 0.3/mm2, 8.1% of CD20+ cells) as well as proliferating tumor cells." (PMID 34943886, 2021). "IL-21 secretion by TH9 has also been shown to increase during anti-tumor response, which stimulates IFN-γ production by CD4+ T cells and is also involved in NK cell activation." (PMID 34012451, 2021). "p-values of BT942 compared with vehicle were 0.027 for CD8+T at day 16 after tumor inoculation in early phase, 0.048 for CD4+T and 0.037 for CD8+T at day 24 after tumor inoculation in late phase, respectively." (PMID 34824364, 2021). "CD20-TCB can redirect the activity of conventional CD4 and CD8 T cells against lymphoma cells by concomitant binding of CD20 on tumor cells and CD3 on T cells." (PMID 33406104, 2021). "It is nonetheless becoming clear that successful immunotherapy-induced anti-tumor immune responses requires both CD8+ and CD4+ T cells." (PMID 33777008, 2021). "Compared with OXA + MnCl2 group, the tumor of OXA + MnP@Lip group had fewer Ki67 expression and more tumor-infiltrating immune cells (CD8+ and CD4+ T cells)." (PMID 34895243, 2021). "In a GBM mouse model, intratumoral R-115 treatment increased the number of CD4+ and CD8+ T cells infiltrating the tumor mass compared to R-LM113." (PMID 34578321, 2021). "Analysis of specific genes involved in CD4+ differentiation and function revealed differential methylation status of TBX21, GATA3, RORC, FOXP3, IL10 and IFNG in tumor CD4+ T-cells." (PMID 34012510, 2021). "Anti-4-1BB's anti-tumor impact probably is related to the increased activity of tumor-specific cytotoxic T lymphocyte and the production of IFN-γ through CD4+ and CD8+ T-cells." (PMID 34267616, 2021). "All samples were stained with a sequential IHC workflow that included a panel of six antibodies for T cells subtyping (CD3, CD4, CD8 and Foxp3), proliferation (Ki67) and tumour recognition (cytokeratin) plus hematoxylin for counterstaining." (PMID 33742063, 2021). "This Th1 cytokine conversation and involvement of both CD4 and CD8 T cells allowed the designing of both anti-viral and anti-tumor vaccines." (PMID 35052724, 2021). "Correlations with immune profiles CD4+, CD8+, and FOXP3+ tumor-infiltrating lymphocytes (TILs), tumoral PD-L1, and stem-related factors NANOG and SOX2 were assessed, and also associations with clinical data and patient survival." (PMID 33494389, 2021). "In a study of 10 fresh tumor samples from untreated TNBC patients, TIGIT overexpression was found in CD8+ and CD4+ TILs, and highly expressed TIGIT and its ligands (CD155 and CD112) were discovered in tumor cells and antigen-presenting cells." (PMID 33717059, 2021). "In particular, PD-1hiCD39+ CD4 TILs expressed the exhaustion transcription factor TOX and the chemokine CXCL13 and were tumor antigen specific." (PMID 33332284, 2021). "CD4+ Th cells and CD8+ cytotoxic T cells play important roles in inhibiting and impeding tumor growth and killing tumor cells." (PMID 34257554, 2021). "The densities of CD4+ and CD8 + memory T cells were negatively correlated with local tumor invasion based on the T stage of the TNM classification." (PMID 33750326, 2021).
tumor (continued). "It has been shown that targeting CD4+CD25+ Tregs cells can improve the chance of successful cancer treatment and tumor rejection responses." (PMID 34055618, 2021). "For example, the infiltration levels with anti-tumor T cells like CD8 T cells, CD4 memory activated T cells, and follicular helper T cells were higher in the low-risk group compared to the high-risk group." (PMID 34880875, 2021). "Cellular immune responses are essential for HCC development, and the CD4+ and CD8+ T subtypes are identified as the primary anti-tumor immune cells." (PMID 33435880, 2021). "M1 macrophages, a highly efficient antigen-presenting cells, can present antigen to tumor specific CD4+ T and CD8+ T cells, and it also has an anti-tumor effect." (PMID 34178648, 2021). "A new study demonstrated that tumor-derived IgG, which is recognized by RP215, suppressed effector T-cell proliferation and promoted tumor growth by reducing CD4+ and CD8+ T-cell infiltration into tumor tissues." (PMID 34226529, 2021). "CD3+, CD4+, CD8+ TILs were significantly correlated with tumor differentiation and ER status (all p < 0.05)." (PMID 33718143, 2021). "Concomitantly, the proportion of tumor-infiltrating regulatory T cells (Tregs, CD25+ FoxP3+), a subset of CD4+ T cells that have pro-tumor influences, was reduced after ZVI@CMC treatment." (PMID 34093872, 2021). "The mixture of L57, L58, L62, and L82 LP-pulsed DC vaccine increased CD4+ T cells, while CpG increased CD8+ T cells in the TME 14 days after tumor inoculation." (PMID 34771674, 2021). "CXCR5 has two transcripts, both localized on the cell membrane, and is expressed by follicular helper T cells (Tfh), circulating CD4+ T cells, B cells, CD68+ macrophages, and tumor cells." (PMID 34947813, 2021). "The results showed that the expression of CCR5, CD3E, CD4, and HLA-DRB1 mRNAs in tumor tissues was significantly higher than that of normal tissues adjacent to the tumor." (PMID 34490269, 2021). "Collectively, these data demonstrate that vvDD-IL-23 treatment elicited potent systemic antitumor effects in late-stage tumor models and the antitumor effect is IFN-γ- CD8+ T cell- and CD4+ T cell-dependent." (PMID 34093846, 2021). "We further analyzed the tumor, spleen, and peripheral blood and found increased numbers of CD3+ T (both CD4+ and CD8+ T cells) in the combination-treatment groups, whereas the numbers of CD4+ FoxP3+ T cells were decreased." (PMID 33859948, 2021). "More tumor antigens and epitopes makes tumor lysate a more effective activator of CD8+ cytotoxic T cells and CD4+ Th cells." (PMID 33732237, 2021). "Tumor immune infiltration analysis results showed that TSPAN11, GPRC5B, TIMP1, and CXCL13 protein levels were significantly positively correlated with CD4+ T cells, macrophages, neutrophils, and dendritic cells." (PMID 33579281, 2021). "Inhibited iDC maturation leads to limited MHC I and MHC II expression, leading to the defective presentation of tumor antigens to naive CD8+ and CD4+ T cells." (PMID 34950576, 2021). "CD4+ cells can act upon the dual secretion effects of IFN-γ and TNF-α by inhibiting tumor angiogenesis." (PMID 33669271, 2021). "Reports suggest that CD4+ and CD8+ TILs highly enriched in the tumor are related to a higher response rate after receiving immunotherapy." (PMID 34513703, 2021). "In comparison, there is a modest increase in IL-12 production, and a substantial increase in IFNγ, CD4+ Th1 cells, and cytotoxic CD8+ T-cell levels, which makes the tumor micro-environment more favorable for responding to anti-PD-1 immunotherapy." (PMID 34267327, 2021). "Control + CP tumors appeared very similar to those treated with CP alone, suggesting that CP was able to increase the level of CD4+, CD8+, and F4/80+ cells in the tumor." (PMID 34063642, 2021). "Th1 polarized CD4+ T helper cells also secrete IFN-γ that help in the promotion and maintenance of anti-tumor CTL responses." (PMID 34220311, 2021).
tumor (continued). "In our study, ICI cluster A exhibited the immune-inflamed phenotype which is characterized by the presence of CD4 and CD8 T cells in the tumor parenchyma." (PMID 34025664, 2021). "Since the majority of LAIR2+ cells within TILs derived from CD4+ T cells, we queried the scRNASeq dataset by comparing the expression profile of CD4+LAIR2+ cells with that of CD4+LAIR2− cells within the tumor-infiltrating fraction." (PMID 35008369, 2021). "We also assessed the co-expression of PD-L1 and markers that define specific immune cell subpopulations: CD4 and CD8 for lymphocytes, FoxP3 for regulatory cells, and CD68 for macrophages, as well as PD-L1 expression in cytokeratin-positive tumor cells." (PMID 34572882, 2021). "At the end of the studies, flow cytometry of single-cell suspensions of tumor tissue was performed, and CD8+ and CD4+ T cell subsets were evaluated." (PMID 33651712, 2021). "CD3+, CD4+, CD8+, CD20+, CD57+, CD68+, and CD163+ cell infiltration was compared in samples from adjacent tissues and the tumor center." (PMID 33995627, 2021). "BT942 also demonstrated significant higher tumor growth inhibition and higher expansion of CD8+ T cells and CD4+ T cells in combination with an anti-PD1 antibody." (PMID 34824364, 2021). "Tumor infiltrating lymphocyte (TIL) populations include CD3+CD4+ and CD3+ CD8+ T cells, which can each be engaged in suppressing tumor growth." (PMID 33669271, 2021). "A good prognosis was observed for patients with tumors that were highly infiltrated by CD20+ combined with CD4+ and CD8+, suggesting that CD20+ TILs support a CD4+ and CD8+ TIL-altered anti-tumor response." (PMID 33726701, 2021). "To understand the underlying evolvement of cellular status in the immune TME, we derived the pseudo-time cell trajectory of the various tumor-infiltrating immune cells, including CD8 T, CD4 T, regulatory T cells (Treg), natural killer (NK), and TAMs." (PMID 34140495, 2021). "Autocrine IL-6 further enhanced IL-10 and IL-21 production by CD4+T cells via STAT3, supporting tumor growth and metastasis." (PMID 34917098, 2021). "The percentage of CD3+ T cells, the proportion of CD4+, CD8+ and Treg subsets and the level of IFNγ production was heterogeneous between tumor samples." (PMID 34290245, 2021). "Increased CD4+ and CD8+ T cells and decreased expression of CD31 in the tumor mass were also observed." (PMID 34200897, 2021). "Tumor shrinkage was accompanied by increased infiltration of T effector, CD4+, and CD8+ cells in HCC, as confirmed by flow cytometry of the tumor-infiltrated lymphocytes (TILs)." (PMID 34140495, 2021). "TILs subsets including CD4, CD8, and FOXP3 should be evaluated, and the balance of tumor suppressive activity conferred by CD8+ Treg cells and CD4+ Treg cells and adaptive tumor responses should be determined in future experiments." (PMID 34797860, 2021). "CD4+ T cells have been reported to inhibit proliferation of effector T cells and to promote the evasion of HCC cells of the anti-tumor immune response." (PMID 34336642, 2021). "The CD4+ Th17-like population marked by high expression of gene KLRB120 is, to our knowledge, the first report of Th17-like cells identified in NSCLC tumor environments by scRNA-seq." (PMID 33953163, 2021). "A significantly lower count of CD4+ and CD8+ tumor-infiltrated lymphocytes was identified in the VTT samples comparing with matched primary tumor." (PMID 34249685, 2021). "The percentage of infiltrated area of CD4+T cells, CD8+T cells, and CD19+B cells in the tumor microenvironment was 3.42% ± 1.08%, 1.76% ± 0.96%, and 4.16% ± 2.20%, respectively." (PMID 34258299, 2021). "In our article, we calculated the correlations between the RRAGB expression and tumor immune infiltration by the spearman’s method and found that the RRAGB mRNA expression was markedly related to B cells, CD4 + T cells and Macrophage cells infiltration." (PMID 34320917, 2021).
tumor (continued). "These clinical studies concluded that DCs-based vaccines are safe and can induce the expansion of circulating CD4+ T and CD8+ T cells which are specific for tumor antigens." (PMID 34830221, 2021). "Listeria monocytogenes is a gram-positive bacterium, capable of selectively infecting APCs, presenting tumour antigens to both MHC-I and -II pathways, resulting in the activation of CD8+ and CD4+ T-cells." (PMID 34065557, 2021). "The expression of SMOC1 was negatively correlated with levels of infiltrating B cells, CD8+ T cells, CD4+ T cells, macrophages, neutrophils, and dendritic cells, as well as gene markers of most immune cells in the LGG tumor microenvironment." (PMID 34869577, 2021). "The efficiency of CD4+ T cell depletion and CD8+ T cell depletion in spleen and tumor tissues was confirmed." (PMID 34262035, 2021). "Because CD4, FOXP3+ T cells tend to aggregate in tumors, qPCR showed variability depending on the tumor section used so we confirmed the decrease in FOXP3 mRNA expression in T cells sorted from tumors (p = 0.0072)." (PMID 34638488, 2021). "Primed CD4+ T cells can provide help to CD8+ T cells, which migrate to the tumor and attack tumor cells that express specific antigens." (PMID 36405502, 2021). "Treg cells accumulated in the tumor tissues also mediate immunosuppression by constraining the activities of CD8+ CTLs and CD4+ T helper cells." (PMID 34439898, 2021). "Tumor-bearing mice on daily CR and cycles of FMD and LCC had a significant reduction in the frequency of FoxP3+CD4+ cells in peripheral blood vs. AL-fed controls." (PMID 34707136, 2021). "In CRC, TGF-β promotes T cell exclusion of both CD4+ and CD8+ cells from the tumor mass and blocks the acquisition of a Th1-effector phenotype." (PMID 34439114, 2021). "Further analysis of the BRCA2mut murine orthotopic breast cancer cell line compared to a syngeneic BRCA2wt line showed increased CD4+ and CD8+ in tumor infiltrating lymphocytes, NK mediated cytotoxicity, α-interferon, and cytokine signaling." (PMID 34195090, 2021). "Although cytotoxic T cells were the subpopulation of TILs observed closest to the tumor cells in our NSCLC cohort; other TILs, such as CD4+, macrophages, NK cells, and B lymphocytes, were also found in proximity to the malignant cells." (PMID 34484217, 2021). "This implies that TEXomiR induces more tumor-specific CTL response and decreases the ratio of CD4/CD8 in the tumor microenvironment." (PMID 33987190, 2021). "We isolated CD4+ T-cells from the tumor infiltrating lymphocytes (TIL’s) and peripheral blood of GBM patients and found increased CD4+ T-cells from multiple lineages (Th1, Th17 and Treg) in the TIL’s compared to blood." (PMID 34012510, 2021). "Tumor and splenic lymphoid DCs, CD69+ NK cells and IFNγ+ CD4+ T cells were significantly increased in CTX-treated tumors compared to controls but there was no further increase in VTX+ CTX-treated tumors compared to CTX alone." (PMID 33452311, 2021). "Interim data from the trial show that the vaccine induces robust CD4+ and CD8+ T cell-mediated anti-tumor immunity with durable objective responses in the vaccinated ICI-experienced melanoma patients." (PMID 34207062, 2021). "Consistently, we did not observe increased production of the type I cytokines IFN‐γ and TNF among CD4+ Tconv and CD8+ T cells within tumours or spleens." (PMID 33838058, 2021). "We found that VISTA was detectable in tumor-infiltrating CD68+ macrophages, CD3+ T cells, CD19+ B cells, CD4+ T-helper cells, and CD8+ cytotoxic T cells." (PMID 33237432, 2021). "polysaccharides significantly inhibit tumor growth through increasing the thymus/spleen index and the number of T lymphocytes (CD4+ and CD8+) in BALB/c CT 26 tumor-bearing mice." (PMID 34563040, 2021). "Given the critical role of DCs in simultaneously tailoring CD4 and CD8 T cell responses during different steps in the anti-tumor immune cycle, the question becomes, how does the TME affect DC physiology and function?" (PMID 34290401, 2021).
tumor (continued). "BT942 treatment resulted in remarkable increase in CD45+, CD3+, CD8+, CD8+ granzyme B+, CD8+Ki67+, CD4+, CD4+Teff, CD4+Teff granzyme B+ and CD4+Teff Ki67+ T cell percentage in MC38 tumor." (PMID 34824364, 2021). "As CYH33 treatment resulted in enhanced infiltration and activation of T cell in tumor tissue, we investigated the roles of CD8+ and CD4+T cells in the activity of CYH33." (PMID 34373258, 2021). "Next, we demonstrated that MSI-H CRC patients with increased IL2RB+ immune cells have an increased abundance of CD3, CD4 and FOXP3 TILs and higher PDL1 tumor and ICOS expression." (PMID 33928242, 2021). "Immunohistochemical analysis of CD4 and CD8 in Hepa1-6 tumor tissues showed that CM-MSNs and anti-PD1 greatly increased the infiltration of both CD4- and CD8-positive cells within the tumor tissues." (PMID 34834226, 2021). "Markers for T cell subsets (CD4, CD8, FoxP3), macrophages (CD68), dendritic cells (CD11c), tumor cells (CD4), vasculature (CD31), and epithelium (cytokeratin) were clearly visualized in the CODEX fluorescent images." (PMID 34795254, 2021). "The absolute numbers of CD8 and CD4 T cells were significantly increased in the MC-38 and E.G7-OVA tumor tissues." (PMID 34249740, 2021). "Hallmark genes for macrophages and T cells were highly expressed in the isolated macrophages, which include CD4+ and CD8+ T cells from tumor and non-tumor tissues, verifying the expected general phenotype of these cells." (PMID 33918618, 2021). "We found that increase in the firing of sensory neurons prevented the increase of immune checkpoint markers of tumor infiltrating CD8 + T cells and CD4 + T cells." (PMID 34784974, 2021). "Tumors in p50(f/f);Lys‐Cre mice possess increased numbers of total and activated CD4+ and CD8+ T cells, and depletion of both of these T‐cell populations accelerates tumor growth." (PMID 33480449, 2021). "The immune types were defined by the morphology of the H&E stain, whereas the distribution of the immune cell subtypes within the tumor was analyzed by IHC of CD8 and CD4 T cells, FoxP3, and CD11b." (PMID 34778030, 2021). "This study analyzed the correlation between the expression of CXCL1-2 and tumor purity, T cell CD8+, T cell CD4+, Macrophage infiltration and other immune cells." (PMID 34123826, 2021). "In silico cytometry, there was a decrease of cancer testis antigen and low tumor infiltrating lymphocyte in patient with high MMP-11 expression: activated dendritic cell, CD8+T cell, CD4+ memory T cell, and memory B cell." (PMID 34038440, 2021). "The positive correlation of ATP6AP1 levels with CD4+ Treg and macrophage levels further explains why patients with higher ATP6AP1 levels had poorer prognoses, since these TIICs can promote tumor growth." (PMID 34228637, 2021). "Depletion of CD4+ T cells, CD8+ T cells and NK cells were all able to abolish the anti-tumor effect of VTX-2337+ cetuximab." (PMID 33452311, 2021). "As for CD4+ T cells, autophagy selectively degrades PU.1, the main TH9 cell transcription factor, and inhibited anti-tumor immunity." (PMID 33990205, 2021). "In contrast, mice depleted of CD4+ T cells, TCRγδ+ T cells, NK cells, or Gr-1+ myeloid cells, remained capable of preventing SCC tumour establishment." (PMID 33925140, 2021). "In a similar manner, the findings of set 2 indicate that the ratio of CD8+ TNFR2+ PD-1+ TILs over CD4+ TNFR2+ PD-1+ TILs was also significantly elevated following chemotherapy and was significantly connected to restrained tumor growth." (PMID 34201054, 2021). "After tumor-infiltrating lymphocytes were extracted, we analyzed PD-1 and CTLA4 expression on CD8+ T cells and Foxp3 expression in CD4+ T cells and CTLA4 expression on CD4+ T cells in the control, PTX, and PTX+US+MB groups." (PMID 34271256, 2021). "Although the current tumor immunotherapy targets mainly focus on CD8+ T cells, the role of conventional CD4+ T cells in tumor immunity has gradually attracted attention." (PMID 34966745, 2021).